IL2 (interleukin 2)
Diseases named in the same sentence as IL2 in open-access papers (continued):
Sharing a sentence is not in itself a finding about the gene and the disease.
tumor (continued). "After gene electrotransfer, tumour growth delay was observed in all groups treated with IL-2 and IL-12 individually and in combination, which was highest in the combination group." (PMID 37629081, 2023). "The intriguing complexity of the IL-2 and IL-2R signaling pathways extends beyond routine immune regulation, with compelling evidence illuminating their roles within the tumor microenvironment (TME)." (PMID 37516849, 2023). "Cytokine analysis of tumor extracts additionally showed that vaccination with ITI-3000 induced significant expression of IFNγ, IL-1β, IL-2, and TNFα, indicative of a strong anti-tumor immune response." (PMID 37711623, 2023). "More potent anti-tumor activity of MBP NK compared to parental NK-92 with soluble IL-2 during in vivo experiment also suggests the importance of efficient and accurate delivery of cytokines in realizing the therapeutic potential of NK cells." (PMID 37056568, 2023). "Tregs suppress anti-tumor immune responses via the secretion of IL-10 and the sequestration of IL-2, and the infiltration of a large quantity of Tregs is often connected with a poor prognosis." (PMID 37345110, 2023). "Th1 cells differentiated from them secrete cytokines such as IL-2 and IL-12, activate antigen-presenting cells, enhance the activity of NK cells, and play an anti-tumor effect." (PMID 36856519, 2023). "For example, anti-PD-1 antibody has been fused with IL-2, IL-15, or IL-21 to expand functional T cells and result in evident tumor remission." (PMID 38049832, 2023). "In the early stage of tumor, IL-2 induced the differentiation of effector CD8+T cells in an autocrine manner, and promoted the activation and proliferation of CD8+T cells." (PMID 37355637, 2023). "documented that combining IL-2 with anti-PD-1 helps overcome tumor resistance to ICIs in mice by reactivating intratumoral CD8+ T cells rather than CD4+ Treg cells." (PMID 38022654, 2023). "IL-2, as a T cell growth and proliferation factor, can induce the expansion of tumor-infiltrating cytotoxic T cells and NK cells." (PMID 36944686, 2023). "IL-2 is an essential cytokine for T-cell survival and the activation of effective cell-mediated immune responses to infection and tumor." (PMID 36891319, 2023). "Moreso, particularly in the iPSC-derived CAR T-cell setting, in vivo models are established with far fewer tumour cells and larger T-cells doses accompanied, by the co-infusion of supportive cytokines including IL-2 and IL-15." (PMID 37998018, 2023). "IL12-MSA binding by tumor-reactive CD8+ T cells was increased by IL2-MSA, and combined IL12-MSA and IL2-MSA resulted in tumor-reactive CD8+ T cell effector differentiation and increased lung tumor control." (PMID 37669107, 2023). "Genistein (4,7,4’-trihydroxy-isoflavone) hampers B16-F10 tumor growth by dose-dependently cytotoxic T-cell activity, IL-2-stimulated NK activity, and basal splenocyte proliferation." (PMID 36768978, 2023). "In particular, IL-2 plays a large role in activating anti-tumor immune responses in the tumor microenvironment." (PMID 36936961, 2023). "The third most frequently implicated hallmark (14 proteins) was “tumor-promoting inflammation”, including markers such as CXCL9, CXCL13, CXL17, IL6, and IL2-RA." (PMID 37264016, 2023). "For example, TNF-α-based therapeutics activate apoptosis, inhibit tumor cell proliferation, and disrupt tumor vasculature, whereas IL-2- or IL-12-based molecules activate and enhance NK and T cells." (PMID 36839658, 2023). "The immunofluorescence staining of tumor tissue sections revealed that tumor‐infiltrating CD8+ T cells in CT26‐bearing mice with FPC2‐IG‐IL‐2 injection was 3‐fold higher than those injected with FPC2‐IG only or with free IL‐2." (PMID 36684086, 2023). "TIL-ACT therapy starts with isolating the natural infiltrating lymphocytes from the tumor tissues, expanding them in vitro, and then infusing these cells back with a high dose of IL-2 to ensure anti-tumor efficacy." (PMID 37427115, 2023).
tumor (continued). "In conclusion, pulsing zoledronate and co-stimulation by the combination of IL-2 and IL-15 lead to significant changes in in vitro anti-tumor activity and in the subclasses of stimulated γδ T cells." (PMID 37539052, 2023). "The combination of paclitaxel and IL-2 significantly inhibited tumor growth and the occurrence of metastasis in tumor-bearing mice." (PMID 37497002, 2023). "IL‐10, IL‐12, and IL‐2 have recently been found to be important for DCs or effector CD8 T cell‐mediated anti‐tumor immunity." (PMID 36891351, 2023). "The early success of high-dose IL-2 cytokine administration along with tumor-infiltrating lymphocytes (TILs) established the essential role of immunostimulatory cytokines to promote the expansion and persistence of adoptively transferred T-cells." (PMID 37958791, 2023). "The Oncept-IL-2 (Merial) includes an IL-2 plasmid that is vectored by a Canary Pox virus administered subcutaneously in the tumor site." (PMID 37376422, 2023). "Interleukin-2 (IL-2) is an anticancer cytokine that triggers human innate and adaptive immunity by stimulating T cell proliferation and lymphocyte infiltration into tumor sites." (PMID 37234162, 2023). "When the vaccine was delivered by combination routes along with IL-2 & IL-12 there was ~ 9 times more tumour suppression than the control vaccine NP alone." (PMID 38112935, 2023). "The in vivo tumor-targeting properties of IL2-7NP2-TNFmut were studied in BALB/C nude mice bearing subcutaneous SKRC52-hFAP tumors." (PMID 37092450, 2023). "Disruption of human IL-2 (hIL-2) alpha chain binding abrogates its preferential use by Tregs, resulting in potent anti-tumour responses." (PMID 37558752, 2023). "Subsequent functional characterization documented strong induction of T cell activation, degranulation and secretion of the “antitumor cytokines” like IFNγ and IL-2 as well as potent induction of tumor cell lysis." (PMID 37122707, 2023). "Several studies suggest that pro-inflammatory interleukins such as IL-2 and IL-12 play an important role in the activation and targeting of cytotoxic T lymphocytes and other immune cells to the tumour microenvironment." (PMID 37629081, 2023). "In contrast, the IL-2 blocking antibodies such as Daclizumab and Basilixumab used in the clinics as immunosuppressive agents, showed inferior anti-tumor efficacy as compared to non IL-2 blocking RG6292 in preclinical models." (PMID 37205201, 2023). "IL-2 is a key cytokine necessary for T-cell survival and activation, enhancing infection and tumor immune responses." (PMID 36891319, 2023). "The cytokines used in the clinical practice of tumor therapeutics are Interferon alfa (IFNα), Interleukin-2 (IL-2), and Granulocyte-Μacrophage Colony Stimulating Factor (GM-CSF), mainly acting as growth promoters of White Blood Cells." (PMID 37998753, 2023). "One subgroup of the cytokines is associated with tumour growth, inflammation, tumour progression and invasion (e.g. IL1, IL17, IL22), and another subgroup includes genes associated with antitumour response (e.g. IL2, IL5, IL12 and IFN family)." (PMID 36649303, 2023). "In the review by Yang Y and Lundqvist A, reported the distinct roles of IL-2 and IL-15 in activating various functions in T and NK cells with a particular focus on the signals that participated in the resistance of tumor-derived immune suppressive factors." (PMID 37520880, 2023). "Surprisingly, the combination treatment with CU06-1004 demonstrated the same extent of tumor size suppression as the treatment with IL-2 alone, and in some cases, it even enhanced the suppression." (PMID 37711172, 2023). "In line with this, Lianjing Zhao and colleagues investigated DCs loaded with the lysate of Newcastle Disease Virus-infected tumor cells to induce more potent anti-tumor immunity by augmenting the production of IL-2 and IFN-γ by T cells." (PMID 38137433, 2023).
tumor (continued). "In previous studies, Tanapoxvirus (TPV) recombinants expressing mouse interleukin-2 (mIL-2) and another expressing bacterial flagellin from Salmonella typhimurium (FliC) have demonstrated anti-tumor efficacy in nude mouse models." (PMID 37628585, 2023). "NKTR-214 exposes tumors to a quantity of pegylated IL2 that is 500 times the amount of aldehyde-based interleukin and provides durable immunity against tumor re-stimulation in combination with anti-CTLA-4 antibodies." (PMID 37808190, 2023). "IL-15 does not bind with CD25 or induce the expansion of the Treg cell population and therefore, shows better anti-tumor activity and lower toxicity than IL-2." (PMID 37510993, 2023). "The presence of TLSs is associated with higher levels of IL-2 in the stroma and lower levels of IL-2 in the tumor compartment." (PMID 37529035, 2023). "Despite the beneficial role of IL-2 in instigating immune responses to attack tumor cells, its ability to expand regulatory T cells (Tregs), potentially dampening anti-tumor immunity, presents a nuanced and paradoxical situation." (PMID 37516849, 2023). "The further hallmarks of T cell activation upon tumor lysis, levels of cytokines released in culture supernatants by T cells were measured, including IL-2, TNF-α and IFN-γ." (PMID 37488603, 2023). "Next, we assessed the immune modulatory potential of mi-IL2 using a 3D tumor spheroid model demonstrating a strong effect on immune cell activation." (PMID 37532747, 2023). "Treatment of U-87, U-138, and GBM neurosphere cell lines has shown elimination of tumor cells in vitro, with induction of interferon gamma and IL-2 production." (PMID 36900205, 2023). "Recent studies have also shown that engineered IL-2 molecules can enhance the efficacy of immune checkpoint inhibitors in cancer treatment by promoting the activation and expansion of tumor-specific T cells." (PMID 37516849, 2023). "While substantial progress has been made, much remains to be understood about the intricate dance between IL-2 and the tumor microenvironment." (PMID 37516849, 2023). "While IL-2 can stimulate immune cells to attack tumors, it can also promote the expansion of regulatory T cells that suppress anti-tumor immunity." (PMID 37516849, 2023). "This competitive interaction reduces IL-2 signaling in DCs, impairing their function and inhibiting the anti-tumor immune response." (PMID 37516849, 2023). "More studies indicated that the IL-2 therapy significantly activated TEXs and enhanced anti-tumor responses, especially when combined with PD1/PDL1 blockade." (PMID 37398660, 2023). "The results showed that the anti-tumor effects of combined IL-2 with PD-1 blockade in March5+/f:Vav1-Cre mice were superior to that in March5+/f mice, which eliminated tumors in 2 out of 8 March5+/f:Vav1-Cre mice." (PMID 37932447, 2023). "IL-4, TGFβ and IL-8 were assessed in low amounts (471 to 820 pg/mg of tumor); CCL2, IL-12, IL-6 and IL-10 in moderate amounts (2825 to 3440 pg/mg of tumor); and IFNγ, TNFα, IL-1β and IL-2 in high amounts (6293 to 13,492 pg/mg of tumor)." (PMID 37526660, 2023). "Gene transfer was performed in both tumours with the control plasmid alone and a combination of the plasmids IL-2 and IL-12, and expression was measured 3 days later." (PMID 37629081, 2023). "After laser irradiation, M@C-HA/ICG increased TNF-α and IL-2 production in the 4T1 tumor-bearing model." (PMID 36986636, 2023). "In the second in vivo experiment, tumours were pre-treated with collagenase and hyaluronidase before electrotransfer of the plasmids IL-2, IL-12 alone and of their combination." (PMID 37629081, 2023). "IL-2, the potent multifunctional cytokine, mainly activated effector and memory T cells and enhanced anti-tumor immunity." (PMID 37398660, 2023). "The administration of IL-2ic without the chemotherapy showed no therapeutic effect, suggesting a synergy between the IL-2 signals and the presentation of antigens released from tumor cells undergoing an immunogenic cell death." (PMID 36705564, 2023).
tumor (continued). "To understand the dose-limiting toxicity associated with combined IL12-MSA and IL2-MSA, we measured the weights of mice for 1 week after the initial treatment on day 7 of tumor growth." (PMID 37669107, 2023). "The Immuno-STAT is a modular fusion protein consisting of a tumor-associated human leukocyte antigen (HLA) peptide complex that delivers interleukin-2 to induce the proliferation of tumor-antigen-specific T cells." (PMID 37046621, 2023). "Together these results suggest a mechanism of synergy between IL12-MSA and IL2-MSA is that IL2-MSA facilitates increased IL12-MSA binding of tumor-reactive CD8+ T cells by inducing IL12R upregulation." (PMID 37669107, 2023). "Dysfunctional tumor-infiltrating lymphocytes have decreased cytolytic activity and impaired production of effector cytokines such as IL-2, IFN-γ, and TNF-α." (PMID 36937769, 2023). "We further combined IL-2 with PD-1 blocking antibody for tumor immunotherapy in March5+/f and March5+/f: Vav1-Cre mice." (PMID 37932447, 2023). "VSIG8-Fc-OX40L led to the TNF-α and IL-2 production in activated PBMCs and increased effector T cells in tumor-bearing mice." (PMID 37936192, 2023). "When treating multiple EphA2+ GBM cell lines with optimized CAR T cell design, treatment showed tumor cell lysis with significant upregulation of interferon gamma and IL-2, and only low levels of induced inhibitory cytokines IL-10 and IL-4." (PMID 36900205, 2023). "The changes in (a) CD8, PD-1, PD-L1, TGF-β1 and FOXP3 levels in the tumor nodules and (b) serum levels of IL-2, IL-10 and TGF-β1 in the MTE-treated mice were similar to those in the AOM/DSS mice, as seen by immunohistochemistry." (PMID 37649480, 2023). "CMC controls tumor growth and increases immunity in the living body by increasing the serum levels of IL-2 and tumor necrosis factor-α (TNF-α)." (PMID 38202616, 2023). "Regarding our in vitro studies and results, 5FU/IL2/CD nanoplexes are more effective than drug solution in the 3D tumor model." (PMID 36839637, 2023). "It was proposed that after consuming IL-2 by Tregs and their proliferation at the tumor site, the IL-2 level for effector TILs decreased." (PMID 37835465, 2023). "In both models 25KbPEI-induced NK cells were demonstrated more effective than IL-2-induced NK cells in infiltrating the tumor and limiting its growth." (PMID 37388731, 2023). "The Th1 subset produces IFN-γ, TNF-α and IL-2, which regulate cellular immunity and play important roles in anti-tumor immune responses." (PMID 37880313, 2023). "In another study vaccine particle was prepared by spray drying method from tumour cell lysates of mouse ovarian cancer cell lines and delivered transdermally alone or in combination with IL-2 and IL-12." (PMID 38112935, 2023). "The nanoplexing of 5-FU with IL-2 showed an increasing trend compared with the control group, while the application of 5-FU as a solution significantly increased the number of tumor-infiltrating CD3+." (PMID 36839637, 2023). "CAR T therapy targeting CSPG4 in GBM neurospheres showed cytotoxic effects against tumor cells, induced IFN-γ and IL-2, and showed proliferation in the presence of tumor cells." (PMID 36900205, 2023). "As the results showed, the down-regulation of PTPRC increased the tumoral (MBA-MD-231) expression of PD-L1 about 1.53-fold as compared to NC group, while the expression level of tumor-derived IL2 was down-regulated." (PMID 37388747, 2023). "Previous studies have found that the combination of IL-2 and antibodies against PD-1 was effective in eliminating a large tumor burden and reducing viral load in a mouse model." (PMID 37106742, 2023). "According to the study, NK cells at rest are not hazardous to tumour cells, however NK cells that have been activated by IL‐2 or IL‐15 have the ability to prevent tumour growth." (PMID 37337404, 2023). "In the subcutaneous tumor model, the level of IL‐2 in blood serum from CAR‐T/NanoSwitch group was significantly lower than that of CAR‐T/FreeSwitch group." (PMID 36755195, 2023).
tumor (continued). "In contrast, in an iPSC-derived NK cell therapy, best anti-tumor response was obtained when a total of 3 doses of NK cells were administrated together with 5 doses of IL-2 cytokine injections into pre-irradiated mice bearing OvCa tumors." (PMID 37949944, 2023). "This highlights the importance of future studies to assess the kinetics of IL-2 production by splenocytes and tumour-infiltrating lymphocytes across a dose range and after various time points following in vivo peptide administration." (PMID 37957274, 2023). "In line with this, engineered MSCs were recently designed to deliver IL-2 to tumor-infiltrating CD8+ T-cells and were thereby able to expand this immune population, inducing systemic anti-tumor immunity and alleviating ICB resistance." (PMID 37928528, 2023). "We previously showed that TILs and blood-derived HER2 CAR-T cells can eradicate PDX tumor models in the human IL-2 transgenic NOG/NSG mouse strain (hIL2-NOG)." (PMID 36765608, 2023). "The development of IL-2-based therapeutics has been accompanied by significant concern regarding its dual impact on tumor-specific T cells and immunosuppressive Tregs." (PMID 37827864, 2023). "MARCH5-knockdown suppressed tumor growth, and sensitized the anti-tumor effects of IL-2 as well as its combination with PD-1 blocking antibody in mice." (PMID 37932447, 2023). "Three-dimensional tumor models consisting of 624-MEL cells were co-cultured with human peripheral blood lymphoid cells (PBLs) in presence of the cytokines IL-2, IL-7, IL-15, IL-21 and IFN-γ." (PMID 37923822, 2023). "In the context of HNSC, implementation of cytokine-based therapy with IL-2, IL-7, and IL-15 has demonstrated the ability to augment T cell activation, expansion, and anti-tumor effector function in patients." (PMID 37926766, 2023). "Cancer cells produce large amount of lactic acid to form an acidic tumor microenvironment, and local high concentration of lactic acid inhibits the function of cytotoxic T lymphocytes and reduces the release of IL‐2, interferon, perforin, and granzyme." (PMID 38089401, 2023). "Andrographolide is credited with potentially inducing apoptosis in several cancer cells and can enhance interleukin-2 secretion by cytotoxic T-lymphocytes for inhibition of tumor growth in mice." (PMID 37653887, 2023). "The data obtained confirmed that aATC effectively inhibited tumor growth, also, IL-2 and INF gamma suppressed the actions and functions of MDSCs and Treg differentiation." (PMID 36982282, 2023). "Repeated intratumoral injections of low-dose IL-2 or single high-dose IL-2 combined with cisplatin resulted in complete tumor regression in 14% and 53% of cases." (PMID 37112681, 2023). "One study reported that the intravenous injection of immune lymphocytes expanded with IL-2 was effective in an animal tumor model." (PMID 37100864, 2023). "Specifically, FMT from long-term survivors into KPC-implanted mice led to activation of CD8+ T cells and increased tumor infiltration, greater serum levels of interleukin-2 (IL-2) and IFN-γ, and improved tumor control." (PMID 36828830, 2023). "Prior to conducting the assay, we identified a subset panel of factors known to mediate the induction of apoptosis in tumor cells: IL-27, IL-1b, IL-2, CXCL10, IL-12p70, G-CSF, IFN-g, TNF-a, IFN-a, CCL2, IL-9, TNF-b, TRAIL, IL-18, IL-21, TSLP." (PMID 37468934, 2023). "TH1, together with naïve T cells, upregulates IL-2 in tumours, resulting in rapid proliferation of lymphocytes, thereby killing the tumour cells." (PMID 36765809, 2023). "IL-21-expressing cells exhibited greater cytotoxicity to tumor cells and greater survival in mice than IL-15 or IL-2 treated CAR-T cells despite higher levels of IFN-γ and Bcl-2 expression." (PMID 37064017, 2023). "The GVAX vaccine, which consists of irradiated tumor cells genetically modified to secrete GM-CSF, is one such example that has been paired with IL-2 to enhance the anti-tumor immune response." (PMID 37516849, 2023).